MET (MET proto-oncogene, receptor tyrosine kinase)
Diseases named in the same sentence as MET in open-access papers (continued):
Sharing a sentence is not in itself a finding about the gene and the disease.
gastric cancer (continued). "In the PANGEA phase II trial, a personalized treatment strategy was applied in gastric cancer patients: antibodies targeting HER2, MET, FGFR2 EGFR PD-L1 or VEGFR2 were added to chemotherapy in first- to third-line treatment in gastric or GEJ cancer patients." (PMID 34680363, 2021). "ERBB2 was most frequently amplified (6 of the 90 gastric cancers, 7%), and KRAS (2 cancers, 2%), PIK3CA (1 cancer, 1%), and MET (1 cancer, 1%) followed." (PMID 34873204, 2021). "In previous studies using tumor tissue, MET amp has been defined using the ratio of MET to CEP7 by FISH, and MET amps were found in up to ~5% of patients with NSCLC or gastric cancer." (PMID 34677235, 2021). "Tivantinib is a selective small molecular inhibitor of cellular mesenchymal-epithelial transcription factor (c-Met or MET) that was clinically developed in various cancers, including non-small-cell lung cancer, colon cancer, gastric cancer, and HCC." (PMID 34804015, 2021). "Since our analysis found there was a concomitant overexpression of MET and HER2 in a subset of GC patients, the activity of volitinib combined with trastuzumab was explored in three gastric cancer PDX models with HER2 and MET positive expressions." (PMID 34557411, 2021). "Afatinib induces the activation of MET and AXL in HER2-driven resistant gastric cancer cell lines, which can be inhibited by cabozantinib so as to reduce resisitance." (PMID 34976824, 2021). "In this study, we investigated the antitumor effects of LY2801653 (merestinib), an oral ATP‐competitive, dual MET, and AXL tyrosine kinase inhibitor, on gastric cancer." (PMID 34766112, 2020). "In conclusion, our study provides evidence for MET and AXL as prognostic biomarkers and potential therapeutic targets in gastric cancer." (PMID 34766112, 2020). "Our study focused on the integrative analyses of HGF and c-MET, and there was consistency between HGF and c-MET in terms of survival prediction, KEGG pathway enrichments and expression level in gastric cancer tissues and peritumor ones." (PMID 32788873, 2020). "In this study, we characterized the expression of EMT-relevant proteins including MET, β-catenin, and E-cadherin in human gastric cancer (GC) cell lines, and further characterized the differential susceptibility of these cell lines compared with the c-MET inhibitor tepotinib." (PMID 32825724, 2020). "In gastric cancer xenograft models, administration of LY2801653 significantly halted MKN45 tumor growth with inhibited MET and AXL phosphorylation activities, decreased cell proliferation and microvessel densities, and increased apoptosis in tumors." (PMID 34766112, 2020). "The present findings established that both MET and AXL were independent predictors of gastric cancer prognosis." (PMID 34766112, 2020). "In our study, LY2801653 demonstrated potent antitumor effects on MET and AXL‐dependent MKN45 gastric cancer cells as well as MKN45‐derived xenograft models by killing tumor cells directly." (PMID 34766112, 2020). "The activity of LY2801653 against moderate MET and AXL expression gastric cancer xenograft model, SNU719, was also explored." (PMID 34766112, 2020). "Taken together, our data indicated that the dual MET/AXL inhibitor LY2801653 successfully targeted MET and AXL by killing tumor cells or affecting tumor microenvironment, representing a promising strategy for the treatment of gastric cancer." (PMID 34766112, 2020). "We evaluated the expression of MET and AXL in a panel of seven gastric cancer cell lines by quantitative real‐time PCR (qPCR) and Western blot analyses." (PMID 34766112, 2020). "Different gastric cancer cell lines were examined regarding their protein levels of BRCA1, BRCA2 and c‐MET using Western blot analysis." (PMID 32686903, 2020).
gastric cancer (continued). "MET and Recepteur d’Origine Nantais (RON), which are RTKs frequently overactivated in gastric cancer, are glycoprotein receptors whose activation have been shown to be modulated by the cellular glycosylation." (PMID 31979110, 2020). "To date, the gastric cancer-related potential therapeutic targets include EGFR, VEGF, MET, FGFR, PI3K/mTOR, and HDAC." (PMID 31816819, 2019). "Anchorage-independent growth of three MET-amplified gastric cancer cell lines (MKN45, SNU-5, KATOIII) was reduced after treatment with MET inhibitors PHA-665752 or crizotinib." (PMID 31557260, 2019). "Genetic alterations in the EGFR, MET, ERBB2, and the PI3K/AKT pathway are often observed in gastric cancer." (PMID 31816819, 2019). "Taken together, MET is a resistance factor for anti-HER therapies in different cancer entities, including gastric cancer." (PMID 31557260, 2019). "The combination treatment of afatinib and MET inhibitor AMG 337 resulted in complete tumor response in a xenograft model with one post-afatinib, MET amplified progression site from one gastric cancer patient." (PMID 31557260, 2019). "Likewise, miR-1 could also suppress gastric cancer cell growth and migration by targeting MET." (PMID 30360560, 2018). "The expression of free MET, miR-21-5p, MDR1, P-gp, and DR5 was significantly increased in drug-resistant gastric cancer cell lines." (PMID 29576621, 2018). "High levels of phosphorylation are observed as a result of RTK amplification and overexpression in few cases which are indication specific like Her2 in breast and gastric cancer, MET in gastric cancer and EGFR in lung and gastric cancer." (PMID 29989001, 2018). "The MET RTK has been nominated a driver oncogene in several tumor types, including lung and gastric carcinomas, with MET‐TKIs being in advanced clinical development." (PMID 30021798, 2018). "PD-L1 and MET co-expression was shown to be an independent factor for poor prognosis that can be used to predict for decreased OS and DFS rates in patients with gastric cancers." (PMID 29137273, 2017). "While MET was positive in 122 cases (31.0%), 57 (46.7%) of which were PD-L1-positive, HGF was positive in 125 gastric cancer (31.7%) samples, 49 (39.2%) of which were PD-L1-positive." (PMID 29137273, 2017). "MET and HGF were expressed in 31.0% and 31.7% of gastric cancers, respectively, where approximately half of which were PD-L1 positive." (PMID 29137273, 2017). "These authors identified a subset of highly-responsive cell lines, predominantly of gastric cancer and NSCLC origin, that displayed MET-gene amplification and were extremely sensitive to MET inhibition." (PMID 28532501, 2017). "MET gene amplifications that result in protein overexpression and constitutive activation of the MET receptor kinase have been reported in NSCLC, gastric cancers and HCC." (PMID 27013592, 2016). "Amplification of seven oncogenes: HER2, EGFR, FGFR1, FGFR2, MET, KRAS and IGF1R has been identified in gastric cancer." (PMID 27437872, 2016). "MET is a pleiotropic RTK, and the MET gene is amplified in a small but prognosis-poor subgroup of gastric cancer patients." (PMID 26848976, 2016). "As the gene encoding the hepatocyte growth factor (HGF) receptor, MET, is a transcriptional target of MACC1, the downstream signaling pathway of HGF-c-MET maybe involved in the mechanism of the“MACC1 regulating the resistant to trastuzumab” in gastric cancer cells." (PMID 27581375, 2016). "In locally advanced gastric cancer, the prognostic values of HGF/MET expression in tumor tissue has also been investigated and found to be a poor prognostic factor in patients who were treated by surgical resection or chemotherapy." (PMID 26716644, 2016). "Approximately 7-17% of advanced gastric cancers have HER2 overexpression or amplification, 2-7% have FGFR2 amplification and 2-8% have MET amplification." (PMID 27437872, 2016).
gastric cancer (continued). "Several studies investigating target genes such as EGFR, MET, and fibroblast growth factor receptor (FGFR) have been conducted since the application of trastuzumab in the treatment of HER2-positive gastric cancer patients." (PMID 27765925, 2016). "Similar to overexpression or gene amplification of MET, these findings support our results that HGF induce the resistance to HER2-target drug in HER2-posotive gastric cancer patients." (PMID 26716644, 2016). "A recent genomic study of gastric cancers identified somatic copy number alterations of seven oncogenes involved in tyrosine kinase/MAP-kinase pathways: KRAS, EGFR, HER2, FGFR1, FGFR2, MET and IGF1R." (PMID 27437872, 2016). "A MET inhibitor, PHA665752, reversed the effects of GALNT2 knockdown on gastric cancer cell survival, invasion, and migration, suggesting that GALNT2 affects GC progression by modifying MET activity." (PMID 26848976, 2016). "MACC1 has been reported as the upstream regulator of c-MET/AKT in hepatocellular cancer, cervical cancer, ovarian cancer, and gastric cancer." (PMID 27581375, 2016). "MET gene amplification resulting in protein overexpression and constitutive activation of the MET receptor has been described in NSCLC, gastric carcinoma and HCC, as well as in preclinical models ‘addicted’ to the MET signaling pathway." (PMID 27013592, 2016). "To identify genes conferring resistance to inhibition of the MET RTK, we conducted a forward genetics screen in the GTL-16 gastric cancer cell line, carrying MET amplification and exquisitely sensitive to MET inhibition." (PMID 25473895, 2015). "To anticipate potential resistance mechanisms, we carried out an in vitro functional screening to identify genes conferring MET inhibitor resistance to GTL-16, a MET-addicted gastric carcinoma cell line with high level amplification of the MET gene locus." (PMID 25473895, 2015). "Five out of 76 (6.6%) patients had a MET gene amplification in FISH analysis (3 esophageal and 2 gastric cancers, all adenocarcinomas)." (PMID 24742823, 2014). "Thus, inhibiting MET pathway might be an effective treatment for gastric cancer." (PMID 24416238, 2014). "We investigated MET mRNA expression status using RNA in situ hybridization (ISH) technique in primary and metastatic lesions of 535 surgically resected gastric carcinoma (GC) cases." (PMID 25364819, 2014). "Certain gastric cancer and NSCLC cell lines display exquisite sensitivity c-MET TKI, but, cells/tumors treated with c-MET TKI eventually develop resistance." (PMID 24205104, 2013). "The ‘EGF- and HGF-dependent stimulation of metastasis in gastric cancer’ map revealed upregulation of HGF and its receptor MET." (PMID 24204627, 2013). "We therefore identified MET amplification at a frequency of 1.5% (4 out of 266 cases), consistent with values determined by FISH analysis in recent studies of gastric cancer." (PMID 23327903, 2013). "This uncertainty led us to determine the prevalence of MET amplification in 266 formalin-fixed, paraffin-embedded (FFPE) specimens of gastric cancer obtained during surgery." (PMID 23327903, 2013). "Prominent validated targets include CDK6, MYC, CCNE2, MET and GMNN and we furthermore validated the regulation of HDAC1 and SIRT1 also in gastric cancer cells." (PMID 21418558, 2011). "Activated MET thus appears to contribute to cell survival, at least in part, through the activation of STAT3 in MET-activated gastric cancer cells." (PMID 21730976, 2011). "We have now shown that forced expression of STAT3-CA attenuated PHA-665752-induced apoptosis in cells with MET activation, indicating that inhibition of STAT3 activity has a role in MET-TKI-induced apoptosis in MET-activated gastric cancer cells." (PMID 21730976, 2011). "c-MET, HGF, and HGF/c-MET levels were also measured in six gastric carcinomas and 33 Head and Neck (HN) carcinomas." (PMID 21283737, 2011).
gastric cancer (continued). "Our in vitro and in vivo results demonstrate that, in MET-addicted gastric cancer cells, the activation of HER (Human Epidermal Receptor) family members induces resistance to MET silencing or inhibition by PHA-665752 (a selective kinase inhibitor)." (PMID 20500904, 2010). "In addition, it has been reported that an HGF-enriched condition significantly reduced the therapeutic potential of MET-TKI in MET-amplified NSCLC and gastric cancer, and additional inhibition of HGF overcame the resistance." (PMID 40299443, 2025). "Galectin-4 further contributes to peritoneal metastasis through interactions with specific membrane proteins such as mesenchymal–epithelial transition factor (c-MET) and CD44, both of which are known to be involved in gastric cancer progression and epithelial-to-mesenchymal transition." (PMID 40710343, 2025). "Notably, treatment with an anti-HGF antibody reduced the number of circulating Tregs expressing c-MET in gastric cancer patients, underscoring HGF’s role in promoting Treg accumulation indirectly through c-MET-expressing monocytes." (PMID 40281554, 2025). "Furthermore, a comprehensive multi-omic analysis of malignant gastric cancers revealed genomic amplifications of established cancer driver genes such as EGFR, ERBB2, MET, FGFR2, and CD44 in gastric cancer with peritoneal metastasis." (PMID 41009730, 2025). "The overexpression rate of MET in gastric cancer is 58%, but it is not recommended as a separate prognostic marker for gastric cancer." (PMID 40296904, 2025). "Further exploration revealed that IL-10 may trigger the activation of the c-MET/STAT3 signaling pathway, fueling gastric cancer progression." (PMID 39664377, 2024). "Zhang and colleagues demonstrated that c-MET siRNA, loaded in HEK293T-derived exosomes, can reverse cisplatin resistance in gastric cancer by inhibiting migration and invasion of gastric cancer cells, promoting apoptosis in vitro and suppressing tumor growth in nude mice." (PMID 39355533, 2024). "Additionally, suppression of PAX3 affects the MET/PI3K axis to inhibit cell proliferation and angiogenesis in gastric cancer." (PMID 38955795, 2024). "Interestingly, treatment with an anti-HGF antibody reduced circulating Tregs among gastric cancer patients, highlighting the role of HGF in fostering Treg accumulation indirectly via c-MET-expressing monocytes." (PMID 39664377, 2024). "Furthermore, another Phase III clinical trial is underway in gastric cancer to assess the efficacy and safety of onartuzumab when administered in combination with mFOLFOX6 for treating metastatic HER2– and c-MET+ gastroesophageal cancer." (PMID 39664377, 2024). "Similarly, in HER2-amplified gastric cancer cells that became resistant to afatinib, a TKI targeting the ErbB family of receptors, as a result of MET amplification, dual inhibition of HER2 and MET effectively suppressed tumor growth." (PMID 39769452, 2024). "The gastric cancer genome is characterized by focal amplification of oncogenes, including receptor tyrosine kinases, such as ERBB2 (HER2), EGFR, ERBB3, VEGF-A, KRAS/NRAS, MET, JAK2, and PD-L1/PD-L2." (PMID 38733489, 2024). "Diagnostic assays of MET overexpression/amplification are not as homogeneous in gastric cancer compared to non-small-cell lung cancer (NSCLC), where the MET exon-14-skipping mutation has been extensively investigated and a clear strategy has been set out." (PMID 37046637, 2023). "MET fusions are rare, may be a primary oncogenic driver in NSCLC, and are also reported in other cancers, including gastric cancer and glioma." (PMID 36999986, 2023). "Regarding gastric cancer, our cohort yielded high-priority target recommendations for targeted therapy, such as MSI, Her2 expression, and PD-L1, while also uncovering rare but promising alterations such as ROS1 fusion and MET-amplifications." (PMID 36572733, 2023).
gastric cancer (continued). "Recently, we demonstrated that MET-amplified gastric cancer patients without co-amplification of other RTKs can benefit from MET inhibitors compared to standard second-line chemotherapy, based on NGS results from tissue specimens." (PMID 38137393, 2023). "The genes MET and HBA1, which were significantly related to oxidative stress, were extracted from mucous cells, and their expression significantly affected the survival and prognosis of gastric cancer patients." (PMID 35659682, 2022). "c-MET overexpression in cancer cells promotes survival of glioma and lymphoma cells via the PI3K signaling pathway and the proliferation of neck squamous cell carcinoma, gastric cancer, and prostate cancer cells via the MAPK and ERK signaling pathway." (PMID 35630066, 2022). "Notably, insulin receptor levels are visualised easily in three of the four gastric cancer cell lines and in the metastatic cells that represent the majority of gastric cancers that are triple-negative for ERBB2, FGFR2 or MET overexpression." (PMID 34554347, 2022). "Our study illustrated long non-coding RNA MIR137HG could promote the progression of gastric cancer through interacting with FUS and affecting a series of its downstream molecules (MET, RHOC, and CTNNB1." (PMID 35733138, 2022). "Accordingly, MET gene amplification predicted higher MPZL3 expression than cell lines without any RTK amplification and MPZL3 levels are positively correlated with MET and ERBB3 expression in LUSC and gastric carcinomas." (PMID 35249128, 2022). "The trendency of MET, HK2, and MYC expression in gastric cancer tissues." (PMID 33718248, 2021). "The co-presence of both MET and FOXM1 is common in patients with gastric cancer." (PMID 33937262, 2021). "As with HER2-amplified gastric cancers, where a cutoff of HER2:CEP17 ratio of >5 was defined for effective trastuzumab treatment, high-level MET amplification (MET/CEP7 >5) was found to give a positive clinical outcome based on the results from a study with crizotinib in non-small cell lung cancer." (PMID 34200749, 2021). "Similarly, co‐expression of c‐MET and its ligand HGF was shown to predict peritoneal dissemination in gastric cancer." (PMID 34542930, 2021). "Cy can also block the activation of the MET/AKT/mTOR axis, so it may be a potential therapeutic agent in the clinical treatment of gastric cancer." (PMID 34830011, 2021). "Our integrative analyses of HGF-c-MET signaling pathway in human gastric cancer patients based on public cancer databases (TCGA and GEO), aiming to better define the characteristics, extent and prognostic prediction of HGF-c-MET signaling pathway involved in gastric cancer." (PMID 32788873, 2020). "However, few reports are available regarding the combinatorial targeting of MET and AXL in gastric cancer." (PMID 34766112, 2020). "With respect to the adaptive response upon MET inhibition observed here, it is noteworthy that PI3K-AKT inhibition, which is a consequence of MET inhibition in MET-amplified gastric cancer cells, can induce HER3 upregulation in other tumor entities via a FOXO-dependent mechanism." (PMID 33374770, 2020). "Blockage of MET and AXL signaling might contribute to the antitumor effects in gastric cancer by inducing growth arrest and apoptosis in gastric cancer cell lines and suppressing cell growth in immunocompromised mice with no obvious toxicities." (PMID 34766112, 2020). "Furthermore, the MET inhibitor KRC-408 suppresses the cell proliferation and angiogenesis of gastric cancer." (PMID 32655941, 2020). "In this study, we investigate the role of c‐MET and PARP inhibition in a gastric cancer model." (PMID 32686903, 2020). "However, as indicated in this paragraph, the relevance of MET as resistance factor to EGFR-targeted therapies was already shown in various cell lines, including gastric cancer cell lines, and in clinical samples." (PMID 31557260, 2019).